IL17A (interleukin 17A)
Diseases named in the same sentence as IL17A in open-access papers (continued):
Sharing a sentence is not in itself a finding about the gene and the disease.
breast cancer (continued). "High salt intake suppressed the tumour growth and lung metastasis in a breast cancer murine model, while an HSD reduced ETBF‐promoted colon carcinogenesis by decreasing the IL‐17A and iNOS expression." (PMID 35747936, 2022). "A study of tumor-infiltrating γδ T cells revealed that IL-17A could polarize inflammatory macrophages and recruit MDSCs to the tumor site of colorectal cancer, and also recruit neutrophils to tumor sites to boost breast cancer metastasis, leading to an immunosuppressive microenvironment." (PMID 31064389, 2019). "We could thus hypothesize that IL-17A/E-induced signaling cascades could affect the protease/anti-protease balance both by up regulating the elastase like protease expression and down regulating Elafin expression in breast cancer cells compared to normal cells." (PMID 26154409, 2015). "To further explore the role of IL-17A in breast carcinoma, we analyzed the expression level in breast carcinoma (BRCA) tissues and normal tissues that were not statistically significant." (PMID 38816694, 2024). "No data was found regarding atrazine or 2,4D exposures, and there is no information concerning IL-17A changes in the context of breast cancer and pesticide exposure." (PMID 37942322, 2023). "Peripheral blood samples were collected from 187 rural working women with breast cancer, occupationally exposed or not to pesticides, to quantify the levels of cytokines IL-1β, IL-12, IL-4, IL-17-A, and TNF -α." (PMID 37942322, 2023). "No data was found in literature about IL-17A deregulation in the context of pesticide exposure and breast cancer." (PMID 37942322, 2023). "Reinforcing such observation, qRT-PCR analysis of TILs expanded from 4 breast cancer patients’ biopsies showed that all the 4 samples were negative or limit to detection (TIL AL) for IL-17B mRNA expression, while half of them expressed IL-17A mRNA." (PMID 29371916, 2017). "Because IL-17A can increase breast cancer cell proliferation through the ERK1/2 pathway, to address the mechanism of PDL1high expression by IL-17A regulation, we next tested whether it depended on the ERK1/2 pathway." (PMID 27935862, 2017). "IL-17A and its receptors are expressed across different tumor types and contribute to a protumor niche via different pathways, such as promoting tumor chemoresistance and proliferation through extracellular signal-regulated kinase 1/2 (ERK1/2) in breast cancer." (PMID 37444399, 2023). "Analyzing gene-expression profile of non-metastatic breast cancer cell lines, that were either treated or not treated with IL17A, Benevides and colleagues identified 1,742 upregulated and 2,592 downregulated genes in the IL17-treated cells compared to untreated cells." (PMID 37427128, 2023). "In conclusion, the serum IL-17A concentration in early breast cancer patients is significantly higher than in the healthy individuals and dominantly depends on the surrogate breast cancer subtype and not on the histological subtype or local extension of the disease." (PMID 37427128, 2023). "In this study, we provide experimental evidence demonstrating an IL-17A production by some human TNBC cell lines and a functional role of tumor-derived IL-17A in concomitantly inducing immune-stimulatory and immune-suppressive responses in a murine model of 4T1 breast cancer." (PMID 32770025, 2020). "Such evidence for a cross-talk between IL-17A and MMP-9 suggest that their simultaneously targeting can be highly beneficial for inhibiting tumor progression in various types of cancer, including breast cancer, gastric cancer, cervical cancer, hepatocellular carcinoma, and lung cancer." (PMID 29983876, 2018). "Besides, unlike findings by other authors, IL-17A or IL-17E did not induce apoptosis in IL-17RB-expressing human breast cancer cells but conversely exacerbated cell resistance to docetaxel." (PMID 27589729, 2016).
breast cancer (continued). "Evidence indicates that IL-17A may also have a role in promoting metastasis by eliciting expansion and polarization of neutrophils that suppress cytotoxic CD8 T lymphocytes in mouse mammary tumors, thereby promoting metastasis, which may be abrogated by neutralization of IL-17A16." (PMID 35136076, 2022). "Analysis of lung Vγ4+ and Vγ6+ cells in mammary tumor-conditioned lungs revealed that inhibition of ICOS, PD-1, or TIM-3 failed to alter the proportion of cells expressing IL-17A, IL-17F, TIM-3, or AREG." (PMID 36480166, 2023). "Out of 122 patients with breast cancer, 64 (52%) had ER-positive tumors; about 20% of ER-positive tumors contained IL-17Ahigh and/or PDL-1high cells, indicating that high expression of IL-17A and PDL1 may not be related to ER status." (PMID 27935862, 2017).
fungal infections (264 papers, 2008 to 2026). "Previously published reports within the setting of fungal infections highlighted that IL-17A and 25 deficient mice have been found to show higher fungal burden after infection with Candida Albicans, which in turn improved by exogenous administration of IL-17A." (PMID 36449073, 2023). "TH17 cells produce IL-17A, IL-17F, and IL-22 that protect the mucosa from bacterial and fungal infection, but have been implicated in inflammation because IL-17 predominantly triggers the influx of neutrophils and tissue repair." (PMID 35453382, 2022). "This is in contrast to the function of IL-17A in this model: While Il17a overexpression protects the mice, lack of signaling through IL-17RA results in increased susceptibility to this fungal infection." (PMID 32174926, 2020). "IL-17, also called IL-17A, is a proinflammatory cytokine, implicated in the development of autoimmunity, tumorigenesis and host defenses against bacterial and fungal infections." (PMID 27552197, 2016). "In line with human studies, mice with a deficiency in IL-17A or its receptor are more susceptible to experimental fungal infection." (PMID 24586147, 2014). "The crucial role of IL‐17 in the immunity against fungal pathogens may be highlighted with bimekizumab, dually inhibiting IL17‐A and F, exhibiting relatively higher risk of fungal infections compared to the other agents." (PMID 39665153, 2025). "Furthermore, T-lymphocytes and Th17-associated cytokines (defective IL-17A, IL-17F, and IL-22 responses to Candida albicans antigens) responsible for the defense against fungal infection emerged from an early age." (PMID 38673639, 2024). "Moreover, IL‐17A production by ILC3s contributes to protection against fungal infection, and IL‐17A deficiency significantly weakens the ability to resist systemic dissemination of C. albicans in mice." (PMID 35844574, 2022). "However, IL-17A has been described as the “signature cytokine” for Th17-cells and is – together with IL-22 – implicated in mucosal immunity against bacterial and fungal infections." (PMID 22216247, 2011). "Because uterine γδ T cells produce IL-17A which has been strongly associated with resistance to fungal infection in mice and in humans, we asked whether γδ T-cell deficiency might negatively impact host-protective responses to intravaginal infection by C. albicans." (PMID 32472066, 2020). "Interleukin 17A (IL-17A) is critical in the host immune response against bacterial and fungal infections, especially at the mucosal surface." (PMID 40821838, 2025). "IL-17A drives neutrophilic inflammation and epithelial injury and plays a crucial role in host defense against bacterial and fungal infections, particularly at mucosal surfaces, but its increased expression can exacerbate lung damage." (PMID 40869413, 2025). "Infection-related signals (e.g., fungal infections, upper respiratory tract infections) mirror IL-17A’s physiological role in mucosal immunity and antifungal defense." (PMID 40408459, 2025). "In vivo expression of IL-17A protected normal mice from the lethal dose of C. albicans, whereas IL-17AR knockout mice had significantly reduced survival during systemic fungal infection." (PMID 41229429, 2025). "Many of these cytokines, such as IFNγ, TNFα, GM-CSF, IL-6, IL-17a, and GRO-α, are associated with protection against fungal infections." (PMID 38469300, 2024). "IL-17A is a cytokine that plays a crucial role in the immune protective response against bacterial and fungal infections." (PMID 39024223, 2024). "IL-17A and F play crucial roles in the adaptive immune system’s response to fungal infections, which are generated by CD4 (specifically Th17) cells and stimulate epithelial cells to express antimicrobial peptides, as well as increase neutrophil trafficking." (PMID 38327523, 2024).
fungal infections (continued). "As regarded fungal infection, the genotypes (GG, GA, and AA) frequency of IL-17A and The genotypes (CC, CG, and GG) frequency of IL-6 G-174C showed significant differences between patient groups and control group p = 0.002,0.01respectively." (PMID 39289412, 2024). "In Candida albicans infections IL-17A acts on epithelial cells inducing them to produce IL-8, a chemotactic factor for neutrophils which then counteract this fungal infection." (PMID 38638687, 2024). "While IL-17A primarily promotes neutrophil recruitment to clear bacterial and fungal infection, it can also lead to tissue damage." (PMID 37937643, 2023). "ILC3s are the primary source of IL-17A in periodontal inflammation and fungal infection, despite the fact that Th17 cells are the primary source of IL-17A in other tissues." (PMID 37047071, 2023). "In general, IL-17A and IL-17F play important roles in chronic inflammation and autoimmunity, controlling bacterial and fungal infections, and signaling mainly through activation of the nuclear factor-kappa B (NF-κB) pathway." (PMID 37600764, 2023). "As an additional mechanism for the control of fungal infections, IL-17A has been shown to be necessary for the development of functional NK cells that are crucial for antifungal defense." (PMID 38567057, 2023). "IL-17A is a cytokine that acts as part of the host defense to bacterial and fungal infections and aberrant IL-17 signaling can lead to excess inflammation." (PMID 35409273, 2022). "Generally, CD4+ TRM cells in viral infection and tumors mainly secreted IFN-γ, while CD4+ TRM cells induced by bacterial or fungal infection mainly expressed IL-17A." (PMID 36471700, 2022). "IL-17A-mediated immunity has been identified as a pivotal host defense mechanism against fungal infections." (PMID 35844574, 2022). "Based on their cytokine secretion and functions during fungal infections, T cells are classified into Th1 (IFNγ, GM-CSF, and TNFα), Th17 (IL-17A/F), Th22 (IL-22), Th2 (IL-4 and IL-13), Th9 (IL-9 and IL-10), Treg (IL-10 and TGFβ), and Tr1 (IL-10)." (PMID 36177012, 2022). "IL-17a plays a role in the protection against bacterial or fungal infection, and it was found that the sensitivity to infection increases in cases with defects in IL-17A or malfunctions in the IL-17 receptor." (PMID 34071276, 2021). "IL-17A is a host cytokine that plays a well-established role in the clearance of bacterial and fungal infections; however, the role of IL-17A in viral infections is poorly understood." (PMID 33824206, 2021). "Although IL-17A is a key factor controlling extracellular bacterial and fungal infection under normal condition, its role in AECOPD seems to be complicated." (PMID 35095906, 2021). "IL-17 (IL-17A), a signature cytokine produced by a subset of T helper cells and plays essential roles in host defense against bacterial and fungal infections." (PMID 34394069, 2021). "IL-17A mediates host resistance to extracellular bacterial and fungal infections by acting as a powerful inducer of neutrophil growth factors, such as granulocyte colony stimulating factor (G-CSF) and cytokines IL-1β, IL-9, and IL-12p70." (PMID 33919521, 2021). "IL-17-producing Th17 cells protect against extracellular bacterial and fungi infections by secreting cytokines IL-17A, IL-17F and IL-22." (PMID 32300208, 2020). "T cells of HDs cultured in the presence of C. albicans produced robust amounts of IFN‐γ, TNF‐α, and IL‐17A, cytokines that are important for immunity to fungal infection." (PMID 32609955, 2020). "The high number of neutrophils and Th17 cells suggests that IL-17A is produced by T cells, which promote the accumulation and enhanced activity of neutrophils in the bronchoalveolar space to fight against fungal infections." (PMID 31887136, 2019). "The finding that IL-33R/ST2 signaling suppresses IL-22 is novel, but a recent study revealed IL-33 regulates IL-17A and IL-22 in fungal infection." (PMID 31057534, 2019).
fungal infections (continued). "While they beneficially mediate resistance to extracellular bacterial and fungal infection via enhanced mucosal production of mucus and antimicrobial peptides, IL-17A and IL-17F are also involved in several autoimmune disorders." (PMID 32010094, 2019). "However, long-term inhibition of IL-6– or IL-17A–induced proinflammatory effects by Ab drugs may hamper the immunity of RA patients and increase the risk of adverse events such as serious tuberculosis infection or fungal infection." (PMID 31194726, 2019). "IL-17A, the first identified member of the IL-17 cytokine family, has the critical function of promoting neutrophil recruitment during bacterial and fungal infection." (PMID 31244826, 2019). "In general, the CD4+ T cells by secreting the cytokines IFN-γ, TNF-α, and IL-17A determine host resistance to severe fungal infections, such as paracoccidioidomycosis, coccidioidomycosis, aspergillosis and candidiasis." (PMID 29520092, 2018). "Accordingly, the implementation of MR-proADM and IL-17A measurements in routine diagnostics for the detection of invasive mycoses should be taken into account." (PMID 28820494, 2017). "In parallel, IL-17A was also shown to be significantly increased in septic patients suffering from a fungal infection in comparison to septic patients with a fungal colonization or without any fungal findings within the first 7 days after sepsis onset." (PMID 28820494, 2017). "CD8+ Tc17 cells, like CD4+ Th17 cells, secrete IL-17A cytokines to activate epithelial cells (mucosal immunity) to secrete antimicrobial products such as defensin to fight against fungal infections." (PMID 29358941, 2017). "The identification of patients with invasive mycoses can be further facilitated by plasmatic measurements of IL-17A as well as MR-proADM, which was furthermore identified to be an early target gene in response to epithelial infections with Candida spp." (PMID 28820494, 2017). "Interleukin-17A (IL-17A) is a cytokine generated by T cells as part of the host defense to bacterial and fungal infections." (PMID 24349309, 2013). "Numerous studies have indicated that Th17 cells and its signature cytokine IL-17A are critical to the airway's immune response against various bacteria and fungal infection." (PMID 23956759, 2013). "Such a role for IL-17A, the founding member of this family, as well as for IL-17F during bacterial and fungal infections has been largely recognized." (PMID 22577359, 2012). "Results from other fungal infection model systems also suggested that multiple cell types can produce IL-17A." (PMID 21359196, 2011). "However, IL-17A plays an important role in host defense against bacterial and fungal infections, and IL-17F is mainly involved in host mucosal defense." (PMID 40149405, 2025). "IL-17A plays a key role in protecting the host from opportunistic fungal infections." (PMID 40863217, 2025). "Moreover, IL-17A, a cytokine produced by T-helper (Th17) cells, is essential for defense against bacterial and fungal infections and plays a key role in autoimmune inflammation." (PMID 39940697, 2025). "Moreover, IL‐17A and IL‐17F play important roles in the host defense against bacterial and fungal infections." (PMID 38660962, 2024). "Given the pivotal role of IL‐17A in bolstering the host's defense against extracellular bacterial and fungal infections, its microbial regulation may be a significant factor contributing to the clinical trial failures of IL‐17A‐targeting monoclonal antibodies." (PMID 38585232, 2024). "IL‐17A is well known to play an important role in fungal infections." (PMID 38660962, 2024). "Interleukin-17A (IL-17A) and Interleukin-17F (IL-17F) are pro-inflammatory cytokines that play crucial roles in the immune system, particularly in host defense against bacterial and fungal infections." (PMID 39335657, 2024).